AMIGO2 (adhesion molecule with Ig like domain 2)
Diseases named in the same sentence as AMIGO2 in open-access papers (continued):
Sharing a sentence is not in itself a finding about the gene and the disease.
pancreatic ductal adenocarcinoma (1 paper, 2024). An infiltrating adenocarcinoma that arises from the epithelial cells of the pancreas. "Additionally, through the combination use of several machine learning methods on multiple pancreatic ductal adenocarcinoma datasets, AMIGO2 is identified as a significant diagnostic and prognostic biomarker in PDAC." (PMID 38189855, 2024). "CCK8 assay shows knock out of AMIGO2 restrains the proliferation of Pancreatic ductal adenocarcinoma cell." (PMID 38189855, 2024). "Then, AMIGO2 siRNA was successfully transfected in two Pancreatic ductal adenocarcinoma cell lines, SW1990 and MPanc-96." (PMID 38189855, 2024). "However, the deep mechanism of AMIGO2 in pancreatic ductal adenocarcinoma cells and M2 polarization of macrophage needed to be further clarified and should be the focus of future research." (PMID 38189855, 2024).
rheumatoid arthritis (1 paper, 2024). A chronic, systemic autoimmune disorder characterized by inflammation in the synovial membranes and articular surfaces. "YTHDC2 and METTL3 jointly regulate the expression of adhesion molecule with Ig like domain 2 (AMIGO2), regulate the proliferation and invasion ability of rheumatoid arthritis synovial fibroblasts, and thereby affect the disease progression of rheumatoid arthritis." (PMID 38790013, 2024).
Stroke (1 paper, 2023). Sudden impairment of blood flow to a part of the brain due to occlusion or rupture of an artery to the brain. "Pan-reactive astrocyte genes (Cxcl10 and Osmr), A1 neurotoxic genes (Amigo2, Ugt1a, Gpc4, H2-D1, and Iigp1), and A2 neuroprotective genes (Ptx3, Thbs2, and Tm4sf1) were all upregulated by NPD1 + RvD1 in the ipsilesional penumbra at 24 h after stroke." (PMID 37270727, 2023).
tumor (23 papers, 2016 to 2026). "The interaction of extracellular matrix receptors causes cancer metastasis, and AMIGO2 promotes the adhesion of tumor cells to endothelial cells, accelerating this process." (PMID 36714025, 2023). "AMIGO2 is a type I transmembrane protein that has been implicated in tumour cell adhesion in adenocarcinomas; however, its importance in GC remains undetermined." (PMID 35296279, 2022). "AMIGO2 has also been linked to the processes of tumorigenicity and metastasis due to its ability to regulate tumour cell adhesion, migration and survival." (PMID 34970543, 2021). "In human adenocarcinomas, AMIGO2 has been implicated in tumour cell adhesion." (PMID 35296279, 2022). "However, the precise mechanism underlying AMIGO2-promoted the adhesion of tumor cells and liver endothelial cells remains unknown." (PMID 35039535, 2022). "AMIGO2 was markedly overexpressed in tumor tissues, and its elevated expression correlated with poor overall and relapse-free survival." (PMID 41583520, 2026). "As the abnormal activation of the PI3K-AKT signaling pathway is a well-known trigger in many cancers 21-23, AMIGO2 has been suggested to participate in the transduction of this pathway, thereby regulating tumor growth and angiogenesis." (PMID 41583520, 2026). "This functional profile provides a mechanistic basis for the metastatic behavior previously reported for AMIGO2 in other cancers and supports its potential role in driving tumor dissemination in PAAD." (PMID 41583520, 2026). "Together, these results establish AMIGO2 as a key mediator of adhesion dependent tumor progression and highlight its potential as a prognostic biomarker and therapeutic target in PAAD." (PMID 41583520, 2026). "Prior studies indicate that AMIGO2 encodes a type I transmembrane protein bearing extracellular LRRs that facilitate protein-protein interactions and ligand binding at the cell surface 14, 17, which may underlie its role in tumor cell-cell/cell-matrix adhesion." (PMID 41583520, 2026). "Xenograft mouse model was established for investigating the effect of AMIGO2 on tumor formation in vivo." (PMID 38978149, 2024). "Combining with the expression of AMIGO2, the increase of AMIGO2 in tumor tissues is significantly correlated to M0 and M2 macrophages (P < 0.0001)." (PMID 38189855, 2024). "AMIGO2 plays a crucial role in various cellular processes, notably including tumor growth, cell adhesion and migration through collagen of gastric cancer cells." (PMID 38978149, 2024). "The single-cell transcriptome and single-cell multi-omics analyses revealed that novel tumor-related genes, such as AMIGO2, ZFP36, BTG1, and DLG5, were mainly upregulated in pituitary neuroendocrine tumors." (PMID 38098508, 2023). "This research led to the discovery of several new tumor-related genes, including AMIGO2, ZFP36, BTG1, and DLG5." (PMID 38275385, 2023). "To evaluate the prognostic value of AMIGO2, we analyzed the correlations between clinicopathological variables and the expression of AMIGO2 in tumor tissues." (PMID 35094710, 2022). "They found that knocking down AMIGO2 expression tumour cells obtained from mice with high liver metastatic potential weakened the adhesion of tumour cells to hepatic vascular endothelial cells and suppressed liver metastasis." (PMID 35296279, 2022). "Our previous studies revealed that amphoterin-induced gene and open reading frame 2 (AMIGO2) promotes the adhesion of tumor cells to liver endothelial cells, followed by the formation of liver metastasis in a mouse model." (PMID 35039535, 2022). "We found that knocking down AMIGO2 expression, which is highly expressed in liver metastatic tumor cells, reduces the adhesion of tumor cells to hepatic endothelial cells and suppresses liver metastasis." (PMID 35094710, 2022). "Our previous study showed that the expression of AMIGO2 in tumor cells that rarely metastasize to the liver enhanced the adhesion between liver endothelial cells and liver metastases." (PMID 35039535, 2022).
tumor (continued). "Later, numerous other studies have reported AMIGO2 expression in gastrointestinal tract cancers, revealing its anti-apoptotic and cell adhesion activities which bestow to the tumor cells a higher metastasis formation capacity." (PMID 35711359, 2022). "In this study, we found that AMIGO2 expression in primary GC tumours correlated with the frequency of liver metastasis." (PMID 35296279, 2022). "Of the 173 tumor specimens evaluated, 28.3% (49/173) had AMIGO2 high expression, while 71.7% (124/173) had AMIGO2 low expression." (PMID 35094710, 2022). "We showed here that Amigo2 mediates tumour cell-liver endothelial cell adhesion, intrahepatic cell attachment and in establishment of liver metastasis." (PMID 28272394, 2017). "Amphoterin-induced gene and open reading frame 2 (Amigo2) was identified as an overexpressed gene in LV12 cells, and knockdown of Amigo2 expression resulted in suppression of liver metastasis via attenuation of tumour cell adhesion to liver endothelial cells." (PMID 28272394, 2017). "In an antisense study, it was found that the inhibition of AMIGO2 expression negatively impact tumor growth and altered chromosomal stability." (PMID 29182684, 2017). "In contrast, integrin α2 44 and the Amigo2 protein (the present study) have been identified as molecules responsible, in part, for liver metastasis in a syngeneic animal model using mouse tumour cells and C57BL/6 mice." (PMID 28272394, 2017). "Collectively, these findings suggest that AMIGO2 may act as a conserved regulator of adhesion- and migration-related signaling across diverse tumor types." (PMID 41583520, 2026). "In cancer biology, AMIGO2 promotes tumor angiogenesis and glucose metabolism, suggesting that it may modulate vascularization and nutrient uptake in energy-demanding tissues." (PMID 40427370, 2025). "Novel tumor-related genes like AMIGO2, ZFP36, BTG1, and DLG5 have been identified." (PMID 38275385, 2023). "Thus, they showed that AMIGO2 drives liver metastasis by homophilic/heterophilic adhesion of tumour cells to liver endothelial cells." (PMID 35296279, 2022). "AMIGO2 was mainly expressed in tumor cells and was rarely expressed in the stroma." (PMID 35094710, 2022). "Most studies have been conducted on the expression of AMIGO2 mRNA in tumor tissues." (PMID 35094710, 2022). "AMIGO2 plays a pathological role in tumour growth, collagen adhesion and migration of GC cells." (PMID 35719914, 2022). "AMIGO2 was located in both the cytoplasm and nucleus of the tumor cells." (PMID 35094710, 2022). "It has been demonstrated that the overexpression of AMIGO2 in parental QRsP-11 cells enhanced the adhesion between liver endothelial cells and tumor cells, whereas AMIGO2 knockdown in LV12 cells attenuated their attachment to endothelial cells, and consequently, liver metastasis." (PMID 35039535, 2022). "Since AMIGO2 expression is involved not only in tumor development but also in tumor progression including acquisition of metastasis, AMIGO2 may be a new molecule that controls cancer stem cell-like function." (PMID 35094710, 2022). "However, the mechanism by which AMIGO2 from tumor-derived EVs mediates the adhesion between tumor and endothelial cells has not been clarified." (PMID 35039535, 2022). "Thus, it was clarified that tumor cells highly expressing AMIGO2 selectively adhere to hepatic endothelial cells expressing AMIGO family molecules by homophilic/heterophilic adhesion patterns to cause liver metastasis." (PMID 35094710, 2022). "High expression was defined as an AMIGO2-positive tumor cell proportion of 30% or higher (≥ 30%)." (PMID 35094710, 2022). "To investigate whether Amigo2 is required for an early phase of liver metastasis (tumour cell attachment to liver endothelial cells), we transfected a firefly luciferase expression vector into LV12 cells (LV12-Luc cells) and QRsP-11 cells (QRsP-11-Luc cells)." (PMID 28272394, 2017).
tumor (continued). "The Amigo2 staining intensity scores were an average of 1.8 ± 0.4 in the liver metastatic lesions, which were significantly higher than the scores in the primary tumour lesions (0.6 ± 0.4, p < 0.01)." (PMID 28272394, 2017). "Faint staining of Amigo2 was detected in primary tumour lesions." (PMID 28272394, 2017). "Thus, Amigo2 regulated tumour cell adhesion to liver endothelial cells and formation of liver metastases." (PMID 28272394, 2017). "However, in all of the cases examined, increased Amigo2 expression was observed in the matched liver metastatic foci, especially on the tumour cell surface." (PMID 28272394, 2017). "In summary, we have shown that Amigo2, which is a member of the Amigo family that shows high species conservation, may be involved in determining liver metastasis by preferential adhesion of the tumour cells to liver endothelial cells." (PMID 28272394, 2017). "In progression group, high expression of AMIGO2 and ASIC1 has been reported to promote tumor metastasis." (PMID 35022521, 2022). "Among these genes, high expression of AMIGO2 and ASIC1 has been reported to promote tumor metastasis." (PMID 35022521, 2022). "Moreover, AMIGO2 expression positively correlates with CD274 (PD-L1) in PAAD, suggesting a possible link to immune-evasive tumor microenvironments and checkpoint activation." (PMID 41583520, 2026). "Through the differential gene expression analysis across all tumor samples and paired normal tissues, we found out AMIGO2 significantly expressed in PAAD and was 12 times higher than normal tissue (median expression of tumor sample = 17.64, median expression of normal tissue = 1.37)." (PMID 41583520, 2026). "Conversely, forced expression of AMIGO2 in non-hepatic metastatic tumour cells enhanced their adhesion to hepatic vascular endothelial cells, resulting in the formation of liver metastases." (PMID 35296279, 2022). "Conversely, it was verified that forced expression of the AMIGO2 gene in non-liver metastatic tumor cells increases the adhesion of tumor cells to hepatic endothelial cells and thereafter forms liver metastases." (PMID 35094710, 2022).
cancer (15 papers, 2016 to 2026). A tumor composed of atypical neoplastic, often pleomorphic cells that invade other tissues. "AMIGO2, a novel member of the gene family encoding type I transmembrane proteins, has been studied in cancer research." (PMID 37063972, 2023). "Since then, several studies discussed the specific cancer-related biological function of the AMIGO2." (PMID 38189855, 2024). "The potential carcinogenic function of AMIGO2 in PDAC was then predicted in silico by pan-cancer analysis and verified in our local PDAC cohorts, two pancreatic cancer cell lines and macrophage cell lines." (PMID 38189855, 2024). "Immunohistochemical imagines of cancer and paracancer shows AMIGO2 and CSF1R are up-regulated on PDAC tissue compare to paracancer tissue." (PMID 38189855, 2024). "As a plasma membrane adhesion molecule, amphoterin-induced gene and ORF-2 (AMIGO2) initially identified as a neurite outgrowth factor has been recently found to play a crucial role in cancer occurrence and progression." (PMID 37438979, 2023). "First, AMIGO2 delivered into HHSECs was transported to the plasma membrane where it functions as an intercellular adhesion molecule that can bind to cancer cells." (PMID 35039535, 2022). "The present study demonstrated that HHSECs incorporated AMIGO2 proteins, and as a result, exhibited enhanced adhesion to cancer cells." (PMID 35039535, 2022). "In conclusion, our study revealed that cancer cell-derived EVs containing AMIGO2 enhanced the adhesion of liver endothelial cells to cancer cells." (PMID 35039535, 2022). "Cancer cells that were strongly stained in the cytoplasm and plasma membrane were considered to have positive AMIGO2 expression." (PMID 35296279, 2022). "Taken together, cancer cell-derived EVs containing AMIGO2 modulates the function of liver endothelial cells, enhancing their adhesion to cancer cells." (PMID 35039535, 2022). "One is that AMIGO2 expressed in cancer cells enhances the adhesiveness of the cancer cells themselves." (PMID 35039535, 2022). "In ovarian cancer, cancer cells with high AMIGO2 expression show a significantly increased growth rate in the abdominal cavity." (PMID 35296279, 2022). "Elucidating the relationship between AMIGO2 expression and organ carcinogenesis and its malignant tumor progression not only improves the prognosis of cancer patients, but also determines target molecules for treatment and prevention." (PMID 35094710, 2022). "Moreover, recent studies have highlighted the potential involvement of AMIGO2 in cancer progression." (PMID 41583520, 2026). "To investigate whether AMIGO family proteins are differentially expressed in PAAD, we used the Oncomine database to compare the mRNA expression of AMIGO2 in different cancer and normal tissue samples." (PMID 41583520, 2026). "Collectively, these findings demonstrate that AMIGO2 serves as a robust prognostic indicator in PAAD, with its elevated expression specifically associated with unfavorable clinical outcomes compared with other AMIGO family members or cancer types." (PMID 41583520, 2026). "Interestingly, a robust correlation between the expression of CSF1R and AMIGO2 in cancer and paracancer tissue are also identified." (PMID 38189855, 2024). "Finally, the role of AMIGO2 as cancer promoter and pivotal factor enrolled in M2 polarization was verified through siRNA transfection and M2 macrophages induction." (PMID 38189855, 2024). "Thus, we identified a novel mechanism by which EV-derived AMIGO2 released from AMIGO2-expressing cancer cells stimulates endothelial cell adhesion to different cancer cells for the initiate step of liver metastasis." (PMID 35039535, 2022). "Most GC cancer cells were moderately to strongly stained with AMIGO2." (PMID 35296279, 2022). "To assess whether AMIGO2-overexpressing cancer cells released AMIGO2-containing EVs, we performed western blotting to measure the EV-derived AMIGO2 protein levels." (PMID 35039535, 2022).
cancer (continued). "Thus, it is possible that the delivered AMIGO2 localizes to the cell membrane of HHSECs where it promotes adhesion to cancer cells." (PMID 35039535, 2022). "Additionally, Amigo2 expression in human cancers was higher in liver metastatic lesions than in primary lesions." (PMID 28272394, 2017). "We also confirmed that Amigo2 expression regulates liver metastasis in human cancers." (PMID 28272394, 2017). "However, the mechanism by which EV-derived AMIGO2 enhances the adhesion of endothelial cells to cancer cells remains unknown." (PMID 35039535, 2022). "However, few studies have investigated AMIGO2 expression using immunohistochemistry in cancer tissues or whether AMIGO2 is related to GC prognosis or metastasis." (PMID 35296279, 2022). "Thus, AMIGO2 expression in cancer cells may enhance the adhesion of cancer cells to liver endothelial cells, thereby facilitating the formation of liver metastasis." (PMID 35039535, 2022). "The phenomenon where cancer cells that do not express AMIGO2 adhere to HHSECs treated with AMIGO2-containing EVs is a prime example of metastatic cancer cell heterogeneity." (PMID 35039535, 2022).
AMIGO2 also shares sentences with these, for which no sentence is quoted: adenocarcinoma (1 paper); Alzheimer disease (1); breast tumor (1); cholestasis (1); endometrial cancer (1); gastrointestinal tract cancers (1); Gliosis (1); glycogen storage disease (1); Hyperammonemia (1); ischemic stroke (1); non-small cell lung carcinoma (1); pituitary tumor (1); Sepsis (1).